GZMB (granzyme B)
Diseases named in the same sentence as GZMB in open-access papers (continued):
Sharing a sentence is not in itself a finding about the gene and the disease.
tumor (continued). "Higher percentages of Granzyme B and CXCR3 were identified on ADAM28 KO CD8+ T cells isolated from tumor-bearing lungs, which can be correlated to the increased tumor density in ADAM28 KO lungs used for this assay." (PMID 30647853, 2018). "The mean frequency of granzyme B+/perforin- CD8+ T cells was significantly lower in PBMC (<5%) compared to SN and tumor (>12%) (p<0.01)." (PMID 29966014, 2018). "Our QIF panel included DAPI to highlight all cells/nuclei in the sample, cytokeratin (CK) to stain tumor epithelial cells, CD3 for T-lymphocytes, granzyme-B (GZB) for T-cell activation and Ki-67 for cell proliferation." (PMID 30097571, 2018). "Of note, immunostainings indicated that the spheres from etoposide-treated cells formed tumors with increased number of tumor-infiltrating cytotoxic T cells, as indicated by enhanced staining of CD8 and granzyme b." (PMID 29765039, 2018). "The data showed that there were significantly more IFN-γ, Granzyme B, perforin, Th1-type chemokine CXCL9, and less TGF-β and angiogenesis markers (CD105 and VEGF) in tumours receiving vvDD-IL-2-RG treatment, compared with other virus treatments." (PMID 30410056, 2018). "On-treatment biopsies showed that Pegilodecakin increased GzmB+, Phospho-Stat3+ and Lag-3+ CD8+ T cells and HLA-A expression in the tumor." (PMID 30400835, 2018). "Results from this analysis are consistent with prior knowledge of EGFR-mutant NSCLC, demonstrating a PD-L1 low, GzmB low, IFNG low and TGFbeta high immune phenotype, suggesting a suppressive tumor microenvironment." (PMID 30400822, 2018). "To investigate the expression level of granzyme B (GZMB) and perforin (PRF1) at steady state, we performed RT-qPCR on sorted CD8+ T cells from PBMC, SN, and tumor." (PMID 29966014, 2018). "Granzyme B was shown to have 1.3-fold upregulation in CD8+ T cells from SN and 2.4-fold increased expression in CD8+ T cells from tumor compared to PBMC (p = 0.125 and p = 0.526, respectively)." (PMID 29966014, 2018). "AZD1775 sensitized murine MOC2 carcinoma cells to granzyme B-dependent KIL lysis, and treatment of immunocompetent MOC2-tumor bearing B6 mice with the combination of AZD1775 and adoptively transferred KIL cells enhanced survival over either treatment alone." (PMID 29925431, 2018). "The involvement of GZMB in the anti-tumor effect of lipid A has been demonstrated by using cells expressing the serpin B9 (PI9-6 cells), a natural protein inhibitor of GZMB." (PMID 29983866, 2018). "We report a tumor-specific differential expression of the CXC-chemokines and Granzyme B, with a remarkable degree of co-expression in individual patients." (PMID 29163806, 2017). "Together, these results demonstrate that dual treatment leads to enhanced infiltration of CD4+ and CD8+ effector T cells, with elevated activation markers (elevated granzyme B, perforin and IFN-γ), as well as reduced Tregs in the tumour tissues." (PMID 28345650, 2017). "ADM has also been shown to indirectly promote an anti-tumor immunoreaction, through the proliferation of tumor-specific CD8+ T cells or the increased permeability of tumor cells to CTL-produced granzyme B." (PMID 28406993, 2017). "We measured granzyme B because it is secreted by CD8+ T lymphocytes and natural killer (NK) cells to mediate apoptosis of cells infected with intracellular pathogens and tumor cells." (PMID 28723951, 2017). "To evaluate the putative functional impact of TIM-3 expression, we monitored both IFN-γ and granzyme B expression by CD8+ TILs 3 days after a single anti-PD-1 injection and 10 days after tumor cell inoculation." (PMID 29273790, 2017). "By analyzing tumor-conditioned media for free pro-angiogenic factors we could detect increased amounts of FGF-1 or GM-CSF in response to DC101 treatment only in the presence of WT- but not GZMB-deficient MC." (PMID 28814715, 2017).
tumor (continued). "Co-culture of the RNA CAR-modified T cells with EpCAM-positive tumor cell lines HRT-18G and SKOV3-Luc stimulated much higher levels of granzyme B release when compared with co-cultures of mock transfected T cells and T cells transfected with mGFP RNA CAR." (PMID 28088790, 2017). "Inhibition of Smad3 also enhanced anticancer activities of NK cells by increasing releases of granzyme B, IL-2 and IFN-γ locally within the tumour tissues and systemically in the circulation." (PMID 28262747, 2017). "We show that mast cells secrete increased amounts of granzyme b upon therapy, which mobilizes pro-angiogenic laminin- and vitronectin-bound FGF-1 and GM-CSF from the tumor matrix." (PMID 28814715, 2017). "Mice received intravenous injections of saline, Granzyme B or GrB/VEGF121 every other day for a total of six treatments, and tumor volume was monitored twice weekly." (PMID 28714916, 2017). "In contrast, a significantly decreased granzyme B expression was detected in stage III (n = 47, p = 0.011 vs. stage I, p = 0.015 vs. stage II) and stages IV malignant tumor tissues (n = 11, p = 0.027 vs. stage I, p = 0.048 vs. stage II)." (PMID 27935860, 2017). "We further observed that tumor-infiltrating CD3+CD56+ NKT-like cells had impaired effector function as shown by decreased IFN-γ, TNF-α, granzyme B and Ki-67 expression." (PMID 27409423, 2016). "Cytolytic enzymes like GzmB are expressed by mature CD8+ and CD57+ cells, and represent a major mechanism for targeted tumor cell lysis by cytotoxic immune cells." (PMID 27310868, 2016). "In order to evaluate the activity of tumor specific cytotoxic T lymphocytes, we analyzed the hepatic expression levels of CD8, FasL, perforin and granzyme B, which are cytotoxic molecules used by CD8+ T lymphocytes, by performed quantitative RT-PCR analysis." (PMID 26727596, 2016). "Immunohistochemically, tumor cells are characterized by CD30, ALK, CD5, TIA-1, Granzyme B, EMA positive staining, and CD2, CD3, CD7, CD4, CD8, CD20, CD79a negative staining." (PMID 27612448, 2016). "Evidence has been reported that autophagy is involved in the degradation of NK-derived Granzyme B (GZMB) in hypoxic tumor cells, allowing tumor cell to escape from NK-mediated killing." (PMID 26910842, 2016). "Undoubtedly, granzyme B is involved in an important pathway for CTL/NK cells-induced apoptosis, and L-Arg significantly elevated the mRNA level of granzyme B in tumor." (PMID 27246354, 2016). "When we analyzed tumor-infiltrating CD8+ T cells, we found that majority of the population produced IFNγ (~80%) and Granzyme B (~70%) in the tumor stroma of WT mice." (PMID 25760243, 2015). "At day 28 after tumor challenge, among protected DC-vaccinated mice, CD4+T-subpopulation expressing granzyme B in C-ter-J28+DC recipient splenocytes had increased compared to that in mDC- and TnMUC1-mDC recipient splenocytes, respectively by 69% and 77%." (PMID 26405163, 2015). "In current studies, we further evaluated XBP1-CTL post-lenalidomide treatment for their specific anti-tumor activity by measuring IFN-γ production and granzyme B expression against the respective HLA-A2+ solid tumor cells." (PMID 27668268, 2015). "Except for OSM, the expression of all anti-tumor genes including TNF-α, PRF1, GZMB, FasL, TNFSF10 and CD40LG were significantly upregulated in CIK cells compared to PBMC, which were negatively correlated with expression profiles of their potential regulators." (PMID 25826780, 2015). "Regarding these results, we concluded that Hsp70-positive tumor cells are killed by Hsp70 plus IL-2 activated, CD94-positive NK cells via granzyme B-mediated apoptosis." (PMID 25926832, 2015). "As markers of such an immune response we analyzed shrinkage of tumor spheroids, CD80/CD86 expression on antigen-presenting cells (APCs), and granzyme B (GrB) expression by CTLs." (PMID 25871398, 2015). "Tumor cells also expressed cytotoxic granules, including TIA-1, granzyme B and perforin, and were often EBV positive." (PMID 26126576, 2015).
tumor (continued). "Compared to the pre-activated tumor-specific CD8+ T cells, tumor-infiltrating CD8+ T cells showed enhanced expression of IFN-γ, granzyme B, and αE(CD103)β7 integrin, the latter of which was found to be important for T-cell retention within the brain." (PMID 26217588, 2015). "CTL phenotypic changes induced by lenalidomide treatment correlated with their enhanced anti-tumor capacity, including IFN-γ and granzyme B production against a variety of solid tumor cancers." (PMID 27668268, 2015). "It was previously believed that CD8+ T mainly comprise CD8+ cytotoxic T cells, Tc cells, which play crucial role in host immune responses to intracellular pathogens and tumor formation by means of the expression of IFN-γ, granzyme B and perforin." (PMID 24523865, 2014). "NK cells can suppress tumor by producing apoptosis-inducing ligands (TRAIL, FasL) and cytotoxic granules (perforin, granzyme B)." (PMID 25587026, 2014). "We demonstrated that in vivo depletion of Tregs and CD8+ T cells in FBL-3-bearing DEREG transgenic mice augments GzmB production by CD4+ T cells and increases FV-specific CD4+ T-cell effector and cytotoxic responses leading to the complete tumor regression." (PMID 22890822, 2013). "Western blot results indicated abundant GzmB expression in cytotoxic cells, even in CD4+T cells which also underwent apoptotic cell-in-cell death inside tumor cells." (PMID 24113190, 2013). "We show here that there is an expansion of tumor-specific CD4+ T cells producing cytokines and cytotoxic molecule granzyme B (GzmB) in the early phase of tumor growth." (PMID 22890822, 2013). "Granzyme B is a well-known cytolytic molecule found in specific granules of CD8+ and CD4+ CTLs as well as in NK cells; it also lyses tumor cells and virus-infected cells." (PMID 23300563, 2012). "Immunohistochemically, tumor cells showed CD3+, CD45RO+, CD5-, CD7-, CD4-, CD8-, CD10-, CD20-, CD30-, CD79a-, CD138-, CD56-, granzyme B-, TIA-1+ and ALK-." (PMID 22931631, 2012). "After accumulation, the T cells stimulated by EGF-SEA became tumor-sensitive CTLs that secreted the tumoricidal cytokines TNF-α and IFN-γ, and the granulolytic proteins perforins and granzyme B." (PMID 21311755, 2011). "By day 7, IFNγ, CSF2, CXCL10, GZMB, PTGS2, TNFα, CD80, CCL22, IL12a, IL13, IL1b, IL6, NOS2, and CTLA4 were significantly upregulated in the tumor-bearing mice bladders and AGTR2 and GATA3 were downregulated." (PMID 22013484, 2011). "Strong associations were found between all infiltrating lymphocytes in the different tumor regions, except for CD3+ T cells and granzyme B expression in the invasive margin and the stroma." (PMID 20385003, 2010). "We observed apoptosis induction as well as anti-proliferative activity on tumour cells cultured with MEDI-565 and T cells, and showed that perforin/granzyme B had a key role in cytotoxicity." (PMID 19953093, 2010). "To further evaluate the function of tumor infiltrating CTL in NPC, we detected Granzyme B positive activated CTL in TIL." (PMID 20064222, 2010). "We found that greater percentage of tumor-infiltrating P14IL-2 (0 h) effector T cells produced granzyme B and IFNγ than P14 and P14IL-2 (24 h) effector T cells (granzyme B: 47.13% vs. 18.59% vs. 30.73%, IFNγ: 35.26% vs. 27.29% vs. 27.26%)." (PMID 19901991, 2009). "The infiltration of the primary tumour by CD3+, CD8+, CD20+, CD68+ and Granzyme B+ had only limited influence on DFS." (PMID 19698134, 2009). "Using this approach, we show that, as a proportion of CD3+ T-cells, tumour infiltrating CD8+ and Granzyme B+ cytotoxic T-cells as well as FoxP3+ Treg were relatively enriched in primary and metastatic tumours when compared to uninvolved lymphoid tissue." (PMID 19698134, 2009).
tumor (continued). "To test the hypothesis that the more potent tumor eradication in mice receiving P14IL-2 (0 h) effector cells is caused by greater cytolytic function of the cells transferred, we checked the production of granzyme B and IFNγ of the tumor-infiltrating lymphocytes of effector cells." (PMID 19901991, 2009). "Tumor tissue was examined by immunohistochemistry for expression of NY-ESO-1, various T cell markers (CD3, CD4, CD8, CD25, FoxP3, TIA-1 and Granzyme B) and other immunological markers (CD20, MHC class I and MHC class II)." (PMID 18923710, 2008). "The cytotoxic effects of anticancer immune cells are mediated by perforin/granzyme-B, Fas ligand and tumour necrosis factor-related apoptosis-inducing ligand (TRAIL), and therefore depend on intact apoptotic responses in target tumour cells." (PMID 17311012, 2007). "In C666/C666-CD137 tumor-bearing, humanized mice, analysis of splenic CD8+ T cells revealed that rhCD137L-MSNs modestly enhanced the expression of granzyme B, while marginally reducing the levels of OX40, HLA-DR, TRAIL and FasL, compared to other treatment groups." (PMID 41328355, 2026). "Moreover, the levels of IFN-γ and granzyme B (GZMB) in spleen T lymphocytes, as well as their cytotoxic activity from IRF7-C435A B16F10 tumor-bearing mice, were significantly higher compared to those in the IRF7-WT group." (PMID 41535256, 2026). "Among mice reconstituted with CD4+ T cells, the HBx‐overexpressing tumours showed increased growth kinetics and final weights, which were accompanied by reduced intratumoural CD4+ T cell infiltration and decreased IFN‐γ and Granzyme B levels." (PMID 41492119, 2026). "They found that CR and PR patients had higher levels of GZMB+ MAIT and IFN-γ+ MAIT (anti-tumor MAIT) after treatment compared to SD patients, and CR and PR patients showed a reduction in IL-17A+ MAIT (pro-tumor MAIT) levels post-treatment, while PD and SD patients did not exhibit this difference." (PMID 41535994, 2026). "By contrast, PD‐1/CTLA‐4 dual blockade neither restored CD4+ T cell infiltration nor enhanced IFN‐γ and Granzyme B production, consistent with its limited anti‐tumour activity." (PMID 41492119, 2026). "Interestingly, CD8+ PD-1+ T cells within the tumor microenvironment are heterogenous with subsets including progenitor PD-1+ TCF-1+ T cells and PD-1+ TIM-3+ GZMB+ effector-like cells." (PMID 40229241, 2025). "This indicates that the combination of Niraparib and Ezetimibe inhibits tumor growth by increasing the infiltration of CD8+ T cells in the tumor tissue, and the increased expression of Granzyme B suggests an enhanced cytolytic effect of the combination therapy on CD8+ T cells." (PMID 40430847, 2025). "The results indicated that combination therapy could suppress tumor growth by converting a tumor with low immunoreactivity into a “hot” tumor, as evidenced by increased infiltration of CD8+ granzyme B+ cytotoxic T cells." (PMID 40002247, 2025). "Flow cytometry analysis revealed an increase in the proliferative (Ki67+), activated (CD69+), and cytotoxic (TNFα+, IFNγ+, GzmB+) CD8+ and CD4+ T cells in tumor tissues and spleens of GL261 tumor-bearing mice treated with cinobufagin, compared to the vehicle-treated group." (PMID 39901195, 2025). "Moreover, it was reported that there was a decrease in the expression of a marker of angiogenesis (VEGF-A) in the tumor after combined treatment, confirming the involvement of the VEGF pathway in the anti-angiogenic effect of granzyme B and TCS." (PMID 40766321, 2025). "Additionally, in vivo experiments using a xenograft mouse model revealed that inhibition of USP13 notably reduced tumor growth, while increasing CD8 + T cell infiltration and boosting GZMB and IFN-γ secretion in tumor tissues, thus enhancing T cell activity." (PMID 41330897, 2025).
tumor (continued). "The expression of 127aa could result in different levels of metabolic excretion in tumor cells, followed by stepwise changes in metabolic pathways in NK cells and, in turn, NK dysfunction, as shown by the decreases in CD56, IFNγ, and GZMB expression." (PMID 39402211, 2025). "Although γδ T cells and CD4 T cells express cytotoxic genes (e.g., GZMB, NKG7), their activity may be suppressed by tumor-induced immune checkpoint signaling and metabolic competition." (PMID 40340807, 2025). "FC analysis further revealed that the combination of USP25 overexpression and anti-PD-1 therapy markedly reduced the accumulation of MDSCs, but strongly increased the number of tumor-infiltrating functional CD8+ T cells, including Granzyme B+ T cells, IFN-γ+ T cells, and TNF-α+ T cells." (PMID 41326342, 2025). "Among these, GZMK+ CD8+ T cells, GZMB+ CD8+ T cells, and NK cells exhibited high levels of effector cytotoxic genes such as GZMA, GZMB, NKG7, PRF1, and GNLY, contributing significantly to anti-tumor immunity." (PMID 40149859, 2025). "Furthermore, we observed higher percentages of tumor-infiltrating IFN-γ+ and GZMB+, CD107a+ cytotoxic CD8+ T cells and IFN-γ+ CD4+cells in AgkcKO mice compared with their counterparts in Agkfl/fl mice." (PMID 39816692, 2025). "Moreover, PD1lo CD8+ TILs from B16 tumours from DR-fed mice displayed elevated TBET and granzyme B (GZMB) expression, consistent with heightened effector function." (PMID 41366157, 2025). "Furthermore, tumor-infiltrating B cells play a role in combating tumor growth and metastasis through the secretion of TRAIL and granzyme B." (PMID 40508074, 2025). "In conclusion, we demonstrated that incorporating an agonistic anti-GITR antibody into the initial TIL culture significantly enhances TIL proliferation, increases the proportion of CD8+ T cells and GzmB+ CD8+ effector cells, and improves anti-tumor efficacies both in vitro and in vivo." (PMID 41280919, 2025). "First, tumor cells themselves may express GZMB, which directly degrades ECM components such as fibronectin, promoting EMT and angiogenesis, thus enhancing the tumor’s invasive and metastatic capabilities." (PMID 41567188, 2025). "Furthermore, co‐injection of BMDMsPRDX1‐KO or RAW264.7PRDX1‐KD cells inhibited syngeneic tumor growth by enhancing CD8+ T‐cell cytotoxicity and secretion of TNF‐α and GzmB." (PMID 41306557, 2025). "It is secreted by tumor cells and acts via the E-type prostanoid receptor 4 (EP4) on NK cells to inhibit their maturation, reduce the expression of cytotoxic molecules such as granzyme B and perforin, and limit their ability to lyse tumor targets." (PMID 40710340, 2025). "This includes the FGFBP2-NKG7 and GZMB-checkpoints programs that were significantly activated in blood-tumor-shared and non-shared clones, respectively." (PMID 40187353, 2025). "On the contrary, RFWD3 overexpression promoted tumor growth and increased tumor weight, inhibited the tumor‐infiltrating CD8+ T cells, Granzyme B‐ and IFN‐γ‐expressing CD8+ T cells, and decreased the number of tumor‐infiltrating NK cells and DCs, but increased the proportion of MDSCs." (PMID 41117130, 2025). "Given that E7 pathway inhibition alone may be insufficient for complete tumor eradication, we engineered ZHPV16E7-GrB—a drug conjugate combining ZHPV16E7 with cytotoxic granzyme B (GrB)." (PMID 40761801, 2025). "The results demonstrated that, compared to the IgG group, EPE significantly increased the mRNA transcription levels of IFN-γ, Granzyme B, Perforin, and CD107a, whereas NK1.1 cell depletion significantly abolished the EPE-induced elevation of these mRNA levels in tumor tissue cells." (PMID 41357886, 2025). "By inducing immediate tumor reduction, expanding effector and memory CD4 + and CD8+ T cell populations, and enhancing interferon-gamma and granzyme B activity, it primes the immune system to eliminate residual micrometastatic disease and reduces the risk of recurrence." (PMID 40115081, 2025).